DES (desmin)
Diseases named in the same sentence as DES in open-access papers (continued):
Sharing a sentence is not in itself a finding about the gene and the disease.
mesenchymal tumors (19 papers, 2014 to 2025). "A diagnosis of malignant mesenchymal tumor was excluded due to negativity for desmin, smooth muscle actin, caldesmon, CD34, CD10, and myoglobin." (PMID 27491291, 2016). "Only CD31, ERG, Ki-67, and Desmin were positive, and malignant mesenchymal tumor was considered." (PMID 38788046, 2024). "After exclusion of reactive processes, carcinomas, and mesenchymal neoplasms, additional EMA, desmin, IMP‐3, and thrombomodulin positivity can be observed in the majority of cases, alongside with BAP1 loss." (PMID 36808895, 2023). "AMFs are characterized by the expression of vimentin, desmin and CD34, suggesting an undifferentiated mesenchymal tumor with preferential myofibroblastic differentiation." (PMID 24894537, 2014). "Some tumors are clearly GISTs with CD117(+) expression and do not exhibit the CD117(−), S100(−), SMA(−), or desmin(−) phenotype characteristic of mesenchymal tumors derived from smooth muscle cells." (PMID 40563584, 2025). "Desmin, vimentin, and calretinin are characteristic immunohistochemical markers of mesenchymal tumours which were negative in our case on IHC." (PMID 27034865, 2016). "Immunohistochemical testing shows that the tumor cells of these mesenchymal tumors are positive for mesenchymal markers, such as SMA, desmin, and S100, while these markers are negative in PM." (PMID 39981620, 2025). "Superficial biopsy and boring biopsy showed unspecific granulation tissues, and immunostaining revealed that the mesenchymal tumor was negative for CD34, c-kit, desmin, and S100 protein." (PMID 32428827, 2020). "Absent reaction to S100, cytokeratin, SMA, desmin, muscle specific actin, smooth muscle myosin heavy chain, and GFAP is used to exclude other mesenchymal tumors." (PMID 25114687, 2014).
angioleiomyoma (18 papers, 2007 to 2025). A benign, slow-growing neoplasm that arises from the dermis or subcutaneous tissue. "Immunohistochemistry was positive for smooth muscle actin and desmin, confirming the diagnosis of angioleiomyoma." (PMID 40661718, 2025). "After surgical removal and histopathology, the mass resulted an angioleiomyoma, vascular type, desmin positive, a very rare neoplasm." (PMID 39994024, 2025). "Surgical excision followed by histopathological and immunohistochemical (IHC) analysis established the diagnosis of angioleiomyoma, marked by desmin-positive smooth muscle fibers and CD34-positive vasculature." (PMID 40755624, 2025). "Desmin is a protein present in smooth muscle and is often used as a marker in the diagnosis of angioleiomyoma." (PMID 38541663, 2024). "The distinctive feature distinguishing MPC from angioleiomyoma is the concentric arrangement of cells and the absence of Desmin staining, a characteristic more frequently observed in MPC." (PMID 38643070, 2024). "Angioleiomyomas feature abundant vascular channels but can be differentiated from MPs as they usually present smooth-muscle fascicles, which stain positive for desmin." (PMID 38637472, 2024). "Our patient had a mixed vascular angioleiomyomas with positive immunohistochemical staining with Desmin for smooth muscle cells." (PMID 17996042, 2007). "However, the cellularity of myopericytomas is generally higher than that of angioleiomyomas, whereas the rate of desmin positivity in myopericytomas is much lower than in angioleiomyomas." (PMID 23742153, 2013). "Further IHC (H caldesmon, Desmin, DOG-1, and ALK) were done for confirmation and to rule the close differentials like Angioleiomyoma, GIST and Inflammatory myofibroblastic tumor." (PMID 40043410, 2025). "Special staining for smooth muscle cells, such as actin, desmin, or myosin, and for vascular endothelium, such as factor VIII or CD31 can aid in differentiating angioleiomyoma from haemangioma, angiofibroma, fibroma, angiomyolipoma, and angiomyosarcoma." (PMID 32859240, 2020). "Additionally, while angioleiomyomas generally exhibit positive staining, they do not display positivity for Desmin within concentric cell structures." (PMID 38643070, 2024). "Angioleiomyoma shares the appearance of concentric perivascular growth pattern with myopericytoma; however, angioleiomyoma tends to lack the distinctive thick-walled vessels and shows negative or focal reactivity for desmin immunohistochemically." (PMID 28214470, 2017). "The presence of myoid cells arranged circumferentially in layers around the vascular lumina and the absence of expression of desmin may also evoke the diagnosis of myopericytoma, but those features are not specific to this tumor and may be encountered in a subset of angioleiomyomas." (PMID 35642047, 2022). "Angioleiomyomas classically show positive immunohistochemical markers like actin, SMA, MSA, desmin, vimentin, h-caldesmon, calponin, and negative markers like HMB45, keratin, and S100." (PMID 38618591, 2024).
spindle cell tumor (17 papers, 2008 to 2026). "Immunohistochemistry, including desmin and smooth muscle actin, helps differentiate it from other spindle-cell neoplasms, with calponin improving diagnostic specificity." (PMID 40525089, 2025). "Immunohistochemistry shows positivity for smooth muscle actin and desmin, which helps distinguish them from other spindle cell neoplasms." (PMID 41209908, 2025). "In our institution, we use SMA and desmin to substantiate the smooth muscle origin of the spindle cell neoplasm we encounter." (PMID 40589689, 2025). "The commonly used immunohistochemical markers for differential diagnosis of spindle cell neoplasms are smooth muscle actin, desmin, CD 34, S100 protein, endothelial markers, and melanocytic markers." (PMID 37143452, 2023). "We diagnosed the tumor as a spindle cell tumor with smooth muscle differentiation because of the positive results of myosin markers such as αSMA, desmin, and h-caldesmon, although some areas with high proliferative activity were observed." (PMID 36117227, 2022). "Histologically, it is described as a highly cellular spindle cell tumor with frequent mitotic activity, staining positive for desmin, myosin, myoglobin, myogenin, and myoD1 markers." (PMID 23936713, 2013). "Although some areas of high proliferative activity were observed, finally, the diagnosis of primary spindle cell tumor of the liver with smooth muscle differentiation was made based on the positive results of muscle markers such as αSMA, desmin, and h-caldesmon." (PMID 36117227, 2022). "Immunohistochemically, NF typically shows strong positivity for SMA and vimentin, with negativity for markers such as S-100 protein, desmin, and CD34, which helps differentiate NF from malignant spindle cell neoplasms, such as sarcomatous lesions." (PMID 41585341, 2026). "Splenectomy revealed a solitary spindle cell tumor composed of bland smooth muscle fibers, diffusely positive for desmin and smooth muscle actin, and negative for C-Kit, CD34, and S100, confirming the diagnosis of splenic leiomyoma." (PMID 41209908, 2025). "Upon total resection, pathology showed a spindle-cell tumor positive for desmin but negative for CD34." (PMID 35509779, 2022). "CT-guided core biopsy was positive for high-grade spindle cell neoplasm (positive for smooth muscle actin, desmin, S100, and CD31; negative for CD34, PAX8, and beta-catenin) and verified by two independent pathologists." (PMID 30558620, 2018). "CT-guided core biopsy was positive for high-grade spindle cell neoplasm (positive for smooth muscle actin, desmin, S100, and CD31; negative for CD34, PAX8, and beta-catenin)." (PMID 30558620, 2018). "Histopathology of RMS mainly presented as embryonic (ERMS) or spindle-cell tumors, which expressed myogenic factors to various degrees, such as myogenin, Myf5, or desmin (not shown)." (PMID 21533183, 2011). "Importantly, these tumors are negative for markers such as SMA, Desmin, EMA, Melan-A, and CD34, which aids in ruling out other spindle cell neoplasms." (PMID 41199828, 2025).
Skeletal myopathy (15 papers, 2008 to 2025). "DRMs are a growing class of skeletal muscle disorders caused by mutations in desmin, αB-crystallin, Z-band alternatively spliced PDZ motif, myotilin, filamin C, and Bag3." (PMID 21445271, 2011). "Mutations in this gene are associated with desmin-related myopathy, a familial cardiac and skeletal myopathy (CSM), and with distal myopathies." (PMID 18691435, 2008). "Desmin is expressed in cardiac, skeletal, and smooth muscle, and many studies have shown that mutations in the human DES gene promote adult-onset skeletal myopathy and, depending on which mutation, one of the three types of familial cardiomyopathies, i.e., dilated, hypertrophic, and restrictive." (PMID 28473771, 2017). "Desmin−/− mice develop a severe dilated cardiomyopathy with a mild skeletal myopathy." (PMID 24922526, 2014).
Ewing sarcoma (14 papers, 2009 to 2025). A small round cell tumor that lacks morphologic, immunohistochemical, and electron microscopic evidence of neuroectodermal differentiation. "Diagnosis of Ewing sarcoma should be based on positive immunohistochemical reactions for vimentin (+++) and CD99 (+++) and negative reaction for desmin, actin, ML, and CD10, associated as in our experience with a high (90%) proliferative index Ki67." (PMID 25960901, 2015). "Ewing sarcomas/PNETs show CD99-positive staining in the cytoplasm and not in the cell membrane and are negative for CK, EMA, WT1, and desmin." (PMID 34193155, 2021).
hypertrophic cardiomyopathy (14 papers, 2010 to 2025). A condition in which the myocardium is hypertrophied without an obvious cause. "Naturally occurring mutations that lead to desmin-related cardiomyopathy, restrictive cardiomyopathy, and hypertrophic cardiomyopathy underscore its relevance to human disease." (PMID 38474073, 2024). "On the other hand, loss-of-function mutations lying within two different KLHL24 functional domains have been recently shown to cause a recessively inherited form of hypertrophic cardiomyopathy, characterized by polyglucan, glycogen and desmin accumulation." (PMID 34740256, 2022). "Conversely, loss of function mutations in KLHL24 are associated with increased desmin expression in cardiac and skeletal muscle tissues of patients affected with hypertrophic cardiomyopathy." (PMID 34740256, 2022). "ASB2 is abnormally downregulated in a mouse model for hypertrophic cardiomyopathy with an associated buildup of desmin levels due to loss of ASB2-directed proteosomal-mediated degradation in cardiomyocytes." (PMID 34968235, 2020). "Vicart and colleagues reported a missense mutation (p.R120G) in the CRYAB associated with a desmin-related myopathy with affected individuals exhibiting signs of hypertrophic cardiomyopathy and discrete lens opacities." (PMID 26402864, 2015). "The immunohistochemical analysis presented both hyperthyroidism and hypertrophic cardiomyopathy groups with a significant loss of contractile protein (desmin) and an increase in interleukin-10, a cytokine characterised by anti-inflammatory properties and activated in myocardial remodelling." (PMID 40564271, 2025). "Desmin-null mice have perturbed muscle architecture, involving both myofibrils and mitochondria, and develop hypertrophic cardiomyopathy." (PMID 29774118, 2018). "Expression of CryAB has been reported to be greatly induced in the cardiac tissue of patients with familial hypertrophic cardiomyopathy, desmin-related cardiomyopathy, and pressure-overload cardiac hypertrophy." (PMID 29088822, 2017). "In conclusion, CMR was able to detect myocardial fibrosis in desmin-related hypertrophic cardiomyopathy." (PMID 21083940, 2010). "We present a rare case of desmin-related hypertrophic cardiomyopathy, CMR revealed fibrosis in the lateral wall of the left ventricle." (PMID 21083940, 2010). "However, human hypertrophic cardiomyopathy tissues exhibited significantly reduced acylcarnitines, whereas the analysis of blood acylcarnitines in our desmin knock-out mice showed an opposite picture." (PMID 36233322, 2022). "The significantly decreased phosphorylation in cTnI, cTnT, RLC, and desmin, but not in cMyBP-C, was discovered in a study with frame shift mutation of cMyBP-C that was carried by hypertrophic cardiomyopathy patients." (PMID 25420047, 2014). "We describe a case of desmin-related hypertrophic cardiomyopathy with myocardial fibrosis detected by CMR, which has not been previously reported." (PMID 21083940, 2010).
inflammatory myofibroblastic tumor (14 papers, 2013 to 2025). A multinodular intermediate fibroblastic neoplasm that arises from soft tissue or viscera, in children and young adults. "Immunohistochemically, the proliferative fibrous/myofibroblasts were positive for desmin, further supporting the diagnosis of inflammatory pseudotumor." (PMID 39777352, 2024). "Most inflammatory myofibroblastic tumors stain positive for desmin, smooth muscle actin, and anaplastic lymphoma kinase (ALK), whereas this patient was non-immunoreactive." (PMID 37123715, 2023). "Myofibroblasts found in inflammatory myofibroblastic tumors, however, stain for alpa-smooth muscle actin, fibronectin, and vimentin, but not for desmin and caldesmon." (PMID 23607022, 2013). "DOG-1, ALK and Desmin were negative, which ruled out the close differentials like GIST, Inflammatory myofibroblastic tumor and leiomyoma and further supporting the diagnosis of myopericytoma." (PMID 40043410, 2025). "Additional stains for desmin, αSMA, S100, and SOX10 were all negative, excluding other differential diagnoses such as leiomyoma, schwannoma, granular cell tumor, and inflammatory myofibroblastic tumor (IMT)." (PMID 41328106, 2025). "In our case, it is easily to rule out diagnoses of inflammatory myofibroblastic tumor (IMT), aggressive fibromatosis, nodular fasciitis (NF), solitary fibrous tumor (SFT), since it is negative for ALK (5A4), β-catenin, SMA, Desmin, and CD34." (PMID 31311568, 2019).
synovial sarcoma (14 papers, 2009 to 2025). "We present a case of metastatic synovial sarcoma from a 26-year-old Hungarian male with unusual immunophenotype showing desmin positivity, which raises diagnostic challenges." (PMID 22966471, 2012). "Intra-abdominal synovial sarcoma, either primary or metastatic, with unusual desmin positivity raised the diagnostic challenge, since a wide range of differential diagnosis could show similar immunophenotype." (PMID 22966471, 2012). "Synovial sarcomas are negative for desmin, actin, S100 protein, and cytokeratin and positive for vimentin and Bcl-2." (PMID 37927755, 2023). "Desmoplastic small blue cell tumors are also positive for desmin, and synovial sarcoma was ruled out using the FISH for the X-18 SYT translocation, which was negative." (PMID 22312368, 2012). "Similar ancillary approaches can be applied to differentiate from myogenic tumor; nevertheless, desmin is usually negative in synovial sarcoma." (PMID 22966471, 2012). "Immunohistochemically, synovial sarcomas show immunoreactivity for cytokeratins, EMA, S-100 protein, are positive for Bcl-2, O-13, Actin and negative for CD34 and Desmin." (PMID 20062586, 2009). "No expression of Desmin, SMA, CD31, Caldesmon, TLE-1, WT-1, and SS18 was in the tumor, which could be differentiated from synovial sarcoma." (PMID 40831926, 2025). "Markers that are commonly expressed on synovial sarcoma cells include epithelial membrane antigen (EMA), BCL-2, and vimentin, while markers such as protein S-100, CD99, CD34, actin, and desmin are mostly negative." (PMID 40130143, 2025). "In common with other synovial sarcomas, the immunohistochemical staining demonstrated some typical findings of synovial sarcoma: the tumor cells were positive for vimentin and CD99, but negative for CD34, Bcl-2, alpha smooth muscle actin, desmin, and S-100 protein." (PMID 24969223, 2014).
muscular dystrophy (12 papers, 2007 to 2025). Muscular dystrophy (MD) refers to a group of more than 30 genetic diseases characterized by progressive weakness and degeneration of the skeletal muscles that control movement. "Mutant forms of desmin (DES) also cause muscular dystrophy, and our analysis associated this protein with the DGC for the first time." (PMID 27099343, 2016). "Studies in desmin null mice and patients with recessive desmin-null muscular dystrophy revealed abnormalities in nuclear and mitochondrial localization and morphology, as well as impaired mitochondrial respiratory capacity." (PMID 32235386, 2020). "We identified causative mutations in desmin (IVS3+3A>G) and filamin C (p.W2710X), and augmented the phenotype data for individuals with muscular dystrophy due to these mutations." (PMID 23155419, 2012). "Overall, EOM myofiber composition remains unchanged despite the lack of desmin, whereas trunk muscle is significantly affected and shows clear signs of muscular dystrophy." (PMID 38431640, 2024). "Since fhl2b was the only Fhl2 paralog differentially expressed in our transcriptomic data of EOMs lacking desmin, we chose to investigate whether fhl2b also could protect muscles other than EOMs in muscular dystrophy." (PMID 38431640, 2024).
myocardial infarction (10 papers, 2015 to 2025). Gross necrosis of the myocardium, as a result of interruption of the blood supply to the area, as in coronary thrombosis. "When feasible, postmortem examination incorporating both desmin immunostaining and Masson′s trichrome staining is recommended, as these techniques are considered reliable for detecting early myocardial infarction or ischemic changes." (PMID 41477563, 2025). "In this study, H&E stained slides and fibronectin, CD59, cathepsin S, troponin T, desmin, and myoglobulin stained immunohistochemistry slides of 20 cases diagnosed with early myocardial infarction were retrospectively analyzed." (PMID 35371665, 2022). "In mice, S59D CRYAB knockin was sufficient to induce desmin mislocalization and myocardial protein aggregates, while S59A CRYAB knockin rescued left ventricular systolic dysfunction after myocardial infarction and preserved desmin localization with reduced myocardial protein aggregates." (PMID 39932799, 2025). "Our data suggests no interplay between phosphorylation and O-GlcNAcylation of desmin in HF post-myocardial infarction." (PMID 30344511, 2018).